PPARG (peroxisome proliferator activated receptor gamma)
Diseases named in the same sentence as PPARG in open-access papers (continued):
Sharing a sentence is not in itself a finding about the gene and the disease.
Insulin resistance (continued). "Our results further add to the growing body of evidence on the association of PPARG Pro12Ala, insulin resistance and subsequent type 2 diabetes." (PMID 24447396, 2014). "The PPARG Pro12 is associated with insulin resistance and this polymorphism interacts with IRS1 Gly972Arg, to increase the risk of T2DM in the mixed-ancestry population of South Africa." (PMID 24447396, 2014). "Mice carrying the equivalent mutation in endogenous PPARγ exhibit hypertension and when bred onto the leptin-deficient genetic background exhibit insulin resistance and metabolic dysfunction." (PMID 25122005, 2014). "In conclusion, the PPARG Pro12 is associated with insulin resistance and this polymorphism interacts with an additional unfavourable genetic polymorphism, IRS1 Gly972Arg, to increase the risk of type 2 diabetes in the mixed ancestry population of South Africa." (PMID 24447396, 2014). "PPARγ production is induced by fatty acids and their derivatives which are linked with adiposity, insulin resistance and sensitivity, and functions of the placenta." (PMID 25258478, 2014). "Many of the T2D susceptibility genes identified by GWAS affect β cell function (cell cycle regulation), and only a limited number of T2D GWAS loci are associated with insulin resistance (e.g., PPARG, FTO, IRS1 and KLF14)." (PMID 23997649, 2013). "The 12Pro allele of PPARG rs1801282 has opposite effects on insulin resistance and BMI in Caucasian subjects, whereas GCKR rs780094 has opposite effects on insulin resistance and lipid levels." (PMID 23101478, 2012). "Treatment of HIV-associated insulin resistance with a PPARγ agonist (rosiglitazone) significantly improved insulin sensitivity assessed with the hyperinsulinemic euglycemic clamp." (PMID 21559208, 2011). "Globally considered, this indicates a partial response of PPARγ-deficient ob/ob islets to insulin resistance." (PMID 22208362, 2011). "The 12Ala PPARγ2 SNP is a loss-of-function allele that been associated with decreased PPARγ activity in adipose tissue, decreased insulin resistance and diabetes in Caucasians." (PMID 20825652, 2010). "Ligand activation of PPARγ in adipocytes is also associated with decreased production of proteins postulated to cause insulin resistance, including TNF-α and resistin." (PMID 20182551, 2009). "The role of PPARγ in HCV 3a-associated insulin resistance in vitro was further assessed bytreating transfected cells with a PPARγ agonist, rosiglitazone." (PMID 19132131, 2009). "A reduction in the level and/or activity of PPARγ has been previously suggested to be linked to the development of diabetic symptoms such as insulin resistance." (PMID 19589179, 2009). "The PPARG mutation is a loss-of-function mutation, but did not manifest dominant negative activity, which is a feature of the other PPARG variants shown to be associated with partial lipodystrophy and severe insulin resistance." (PMID 18232732, 2008). "Of particular note are time-resolved fluorescence polarization studies by Kallenberger and Schwabe on the human P467L PPARγ mutant that causes insulin resistance and early onset hypertension." (PMID 18617990, 2008). "It appears that the Pro12Ala polymorphism of the PPARG genemay be a modifier of insulin resistance in women with PCOS, which can have aprofound influence on fertility (see Section 4.1)." (PMID 18309368, 2008). "Conversely, insulin resistance associated genetic variants of PPARG, ADIPOQ and ENPP1 were found to be only associated in obese subjects." (PMID 18498634, 2008). "For example, severe insulin resistance (with or withoutovert T2DM) has proved to be a remarkably consistent finding insubjects with loss-of-function PPARγ mutations, beingevident even in early childhood in affected individuals." (PMID 17389771, 2007). "We describe mutations in the DNA and ligand binding domains of human PPARγ in lipodystrophic, severe insulin resistance." (PMID 17011503, 2006).
Insulin resistance (continued). "The discovery that PPARγ is a target for TZDs, which act by enhancing tissue insulin sensitivity, prompted screening of a cohort of subjects with severe insulin resistance, with identification of two missense PPARγ mutations (P467L, V290M) in unrelated cases." (PMID 17011503, 2006). "Notably, PPARγ overactivation is also associated with insulin resistance, establishing a vicious cycle of “lipotoxicity-metabolic dysregulation.”56 Intervention studies indicate that PPARγ inhibition significantly alleviates cadmium-induced hepatic steatosis." (PMID 41550743, 2026). "Furthermore, reactive oxygen species (ROS) accumulation is closely linked to PPARG signaling, and PPARG agonists significantly ameliorate the pathological manifestations of insulin resistance." (PMID 41465406, 2025). "Heterozygous LoF in PPARG has previously been linked to familial partial lipodystrophy, characterised by the loss of subcutaneous fat from the extremities and metabolic abnormalities such as insulin resistance and hypertriglyceridemia." (PMID 39809772, 2025). "In this context, it is notable that antidiabetic drugs such as thiazolidinediones, which are PPARγ agonists used to treat insulin resistance, can activate PXR, potentially causing adverse metabolic effects or insulin resistance via interfering with PPARγ signaling." (PMID 40726484, 2025). "Furthermore, studies examining PPARG mutations in human adipose have revealed several associated metabolic disturbances such as lipodystrophy, diabetes, hypertension, and insulin resistance." (PMID 39202377, 2024). "Heterozygous LoF in PPARG has previously been linked to familial partial lipodystrophy, characterised by the loss of subcutaneous fat from the extremities and metabolic abnormalities such as insulin resistance and hypertriglyceridemia 24–27." (PMID 38633783, 2024). "miR-27a suppresses PPARγ in skeletal muscle cells to cause insulin resistance." (PMID 39220365, 2024). "FFC-EtOH did not significantly affect the gene expression of sterol regulatory element-binding protein (Srebp1c) or peroxisome proliferator-activated receptor gamma (Pparg), both of which are lipogenic transcription factors that are implicated in insulin resistance, compared to Chow." (PMID 37134024, 2023). "Indeed, previous studies reported that heterozygous PPARG-deficiency protected mice from the development of insulin resistance due to adipocyte hypertrophy under a high-fat diet." (PMID 37076894, 2023). "In contrast, the subcutaneous adipose tissues of obese individuals and patients with type 2 diabetes display reduced PPARG activity, and PPARG activation in adipocytes was reported to be sufficient to reduce insulin resistance, hallmark of hypertrophic obesity." (PMID 37076894, 2023). "Given that skeletal muscle is a major site of fuel oxidation, the loss of muscle PPARγ could affect and impede the utilization of FA and glucose by skeletal muscle, contributing to the development of insulin resistance and T2DM." (PMID 37334286, 2023). "More precisely, severe hypertension, along with other health conditions including insulin resistance, diabetes, or dyslipidemia, may be partly attributed to the loss of basal transcriptional activity caused by mutations in the wildtype PPARγ." (PMID 36831316, 2023). "Therefore, the disrupted regulatory mechanism of PPARγ signaling is the primary cause of insulin resistance and glucose intolerance." (PMID 37907845, 2023). "In addition, a previous study found that in samples with BMI greater than 30 kg/m2, PPARG Pro12 gene polymorphisms with C/C genotype had higher glucose level and insulin resistance." (PMID 35265101, 2022). "Previous studies have showed that Pro12Ala and His447His polymorphisms of the PPARG might be protective factors of insulin resistance in PCOS women." (PMID 36105080, 2022).
Insulin resistance (continued). "Genetically modified mice encoding an allele of PPARγ cannot be phosphorylated at Ser273 and could protect from insulin resistance probably by inhibiting Gdf3." (PMID 36551260, 2022). "In addition, 30 splice variants (SVs) of PPARG have been identified from tumor cells, and some SVs are associated with insulin resistance and metabolic diseases." (PMID 36555903, 2022). "PPARγ variants cause lipodystrophy, insulin resistance, and diabetes." (PMID 34764936, 2021). "In addition, heterozygous PPARγ-deficient mice developed lipoatrophy, hyperglycemia, and insulin resistance when treated with HX531 in a HFD setting." (PMID 34440929, 2021). "Indeed, deletion of Rora from the liver specifically results in exacerbated weight gain and insulin resistance associated with enhanced transcriptional activity of PPARγ resulting in uncontrolled lipogenesis." (PMID 32973801, 2020). "PPARγ-deficient macrophages are resistant to M2 polarization and promote insulin resistance." (PMID 32733471, 2020). "In short, the dysregulation of PPARG can cause insulin resistance and CKD." (PMID 32604723, 2020). "Furthermore, PPARγ3RA/+ mice showed impaired glucose tolerance and insulin tolerance compared to their WT counterparts, suggesting that PPARγ 3RA mutations in mice exacerbate HFD-induced insulin resistance." (PMID 32973516, 2020). "Therefore, it is likely that the dramatic reduction in limb and gluteal fat found in subjects with PPARγ mutations contributes to their insulin resistance." (PMID 32708786, 2020). "Under systemic conditions in a mouse model, the adipocyte-specific MED19 knock-down in adipose tissue leads to lipodystrophy, hepatic steatosis and insulin resistance which is associated with a change in the PPARγ-mediated gene expression, but also with beiging of BAT." (PMID 33233602, 2020). "PPARγ Ser273 phosphorylation has been linked with the development of insulin resistance." (PMID 30871156, 2019). "As previously indicated, PPARγ is a key regulator of fat metabolism and therefore, targeting this nuclear receptor can be useful in metabolic disorders such as lipodystrophy, dyslipidaemia and insulin resistance, which are all commonly associated with cART57." (PMID 31263138, 2019). "In our previous studies, two antidiabetic drugs, specifically metformin and pioglitazone (a PPARγ agonist), that improve insulin resistance and cross the blood-brain-barrier, reduced the risk of dementia in a dose-response pattern in patients with type 2 diabetes mellitus." (PMID 31085804, 2019). "Adipocyte-specific disruption of Fsp27 causes hepatosteatosis and insulin resistance in high-fat diet-fed mice, indicating that PPARγ agonist-induced expression in adipose tissue might predominate the effect of fatty liver in terms of whole-body metabolism." (PMID 30871156, 2019). "PPARγ agonists are used to treat insulin resistance associated with metabolic syndrome and T2DM." (PMID 31440258, 2019). "Furthermore, it has been reported that the use of PPARγ agonists reverse the insulin resistance associated with late pregnancy in murine models." (PMID 30037087, 2018). "PPARγ activation enhances insulin sensitization in skeletal muscle and increases glucose metabolism and adipogenesis in white and brown fat tissue, cause-effect relationship between insulin resistance and the stimulation of muscle protein breakdown." (PMID 30647761, 2018). "Similarly, rare mutations in the ligand-binding domain of PPARγ (Arg425Cys and Phe388Leu) have been found in patients with insulin resistance." (PMID 30012954, 2018). "In humans, dominant negative PPARγ mutations are associated with obesity, dyslipidemia, and severe insulin resistance, whereas a common polymorphism (Pro12Ala) has been shown to decrease PPARγ receptor activity, improve insulin sensitivity, and decrease T2DM risk." (PMID 29747466, 2018).
Insulin resistance (continued). "The loss of subcutaneous WAT evoked by 10,12 CLA is similar to the effects of human partial lipodystrophy, in which peripheral adipose tissue is redistributed to visceral adipose depots or ectopic sites such as the liver, and is often linked with defective PPARγ signaling and insulin resistance." (PMID 28245284, 2017). "PPARγ controls the genes encoding peptides or proteins involved in insulin resistance." (PMID 28243251, 2017). "Even if such associations have been inconsistent across different studies, there is evidence in our work in the Global Lipids Genetics Consortium that there are associations of variation in PPARG with lipid fractions, presumably due to high correlations between insulin resistance and dyslipidemia." (PMID 29303622, 2017). "Therefore, disturbed regulatory mechanism of PPARγ signaling in HFD-fed RORαLKO mice would be the main cause of the insulin resistance and glucose intolerance." (PMID 28757615, 2017). "Muscle-specific PPARγ-deficient mice develop increased adiposity and whole body insulin resistance." (PMID 25912041, 2015). "Besides, it was shown that depletion of PPARγ in adipose tissue causes insulin resistance, since decreased PPARγ action in mature adipocytes, leads to reduced expression of key genes required for insulin signaling in adipocytes." (PMID 25534067, 2014). "Interestingly, PPARG is one of the few genes that were confirmed to be associated with insulin resistance, Significantly greater insulin sensitivity was reported in not only nondiabetic alanine (Ala) carriers, but also the diabetic patients." (PMID 23997649, 2013). "Therefore, due to relative PPARγ deficiency mitigates some physiological causes of insulin resistance, so make a condition as therapeutic maneuver with aimed to produce the same effect as PPARγ deficiency." (PMID 24330836, 2013). "However, the insulin-sensitising effect of the PPARG 12Ala allele on skeletal muscle is either lost or masked by insulin resistance in patients with type 2 diabetes mellitus." (PMID 23799144, 2013). "Although the therapeutic potential of PPARβ/δ for metabolic diseases such as insulin resistance, dyslipidemia, and other associated liver pathologies deserves further investigations, agonists of PPARγ and PPARα have been developed as relevant drugs to treat these disorders." (PMID 23024649, 2012). "Experiments in mice indicated that elevated RBP4 levels cause insulin resistance, suggesting that the improvement of glucose metabolism by PPARγ activation may be through the reduction of circulating RBP4 levels." (PMID 23145084, 2012). "However, heterozygous PPARG-deficient mice showed protection from insulin resistance induced by a high-fat diet and an increased number of small-sized adipocytes." (PMID 22937051, 2012). "The point mutation P467L in human receptor PPARγ has been shown to be associated with adverse effects for human health and well-being, resulting in lipodystrophy, severe insulin resistance, fatty liver, hypertension, and lowered adiponectin levels in circulation." (PMID 21933390, 2011). "In this study, we evaluated the relationship between the PPARγ mutation and insulin resistance." (PMID 20334678, 2010). "Indeed, it has recently been shown that muscle-specific PPARγ deletion in mouse caused insulin resistance." (PMID 20981297, 2010). "C161→T substitution at exon 6 of the PPARγ gene has been found to be associated with insulin resistance in Hispanic and non-Hispanic white women, considers to be a better predictor of fasting insulin levels and insulin resistance than P12A." (PMID 20334678, 2010). "Loss-of-function ordominant-negative mutations in the PPARG gene in humans, and genetically-induced PPARγdeficiency in mice are responsible for lipodystrophic syndromeswith insulin resistance, showing the primarily involvement of PPARγdefects in adipose tissue development and metabolic roles." (PMID 19125203, 2009).
Insulin resistance (continued). "Disturbances in the production of these factors may contribute to the development of insulin resistance or impaired insulin secretion: PPARγ activation is also associated with beneficial effects on the expression and secretion of a whole range of adipokines." (PMID 20182551, 2009). "PPARγ +/− mice are protected against diet- and age-induced insulin resistance, whereas humans with the PPARG FS variant, which appears to behave as a null allele, manifest exaggerated hypertriglyceridaemia and insulin resistance with weight gain (unpublished data)." (PMID 18232732, 2008). "Thustherapeuticmaneuvers that could produce relative PPARγ deficiencymight be of clinicalvaluefor the treatment of insulin resistance in old age." (PMID 18317516, 2007). "Subsequently, two further heterozygous mutations in the ligand binding domain (LBD) of PPARγ (R425C; F388L) have been described, with recognition that in addition to insulin resistance the phenotype also includes a stereotyped pattern of partial lipodystrophy (PLD)." (PMID 17011503, 2006). "Additionally, genetic mutations, for example in the peroxisome proliferator-activated receptor gamma (PPARγ) gene, may play a role in the development of insulin resistance by leading to altered insulin levels, molecular signaling and lipid metabolism." (PMID 38791018, 2024). "Furthermore, PPARγ activation in mature adipocytes improves insulin sensitivity by inducing the expression of several genes involved in the insulin signaling cascade, and its downregulation is associated with insulin resistance." (PMID 38820505, 2024). "Moreover, a mouse lineage with PPARγ S273A mutation was generated via homologous recombination in mouse embryonic stem cells (mESCs), in 2020, and has demonstrated protection against the development of insulin resistance in response to a high-fat diet (HFD)." (PMID 37189379, 2023). "Thiazolidinedione (TZD) is a class of oral antidiabetic drug that improves insulin resistance by acting as an agonist to the nuclear hormone receptor of peroxisome proliferator-activated receptors gamma (PPARγ), and PPARγ activation may affect the risk of cancer." (PMID 37686552, 2023). "Additionally, PPARγ is associated with the development of insulin resistance and type 2 diabetes." (PMID 37338602, 2023). "Indeed, PPARγ mutation in humans is associated with insulin resistance, T2D, and liposystrophy." (PMID 34613819, 2021). "Finally, we conclude that the insulin resistance provoked by PPARγ phosphorylation is linked to a differential coregulators recruitment, which may promote dysregulation in gene expression." (PMID 33329381, 2020). "Moreover, constitutive PPARγ activation in the mouse skeletal muscle decreases intramuscular lipid accumulation, induces a shift towards the oxidative fiber type, and protects against susceptibility to diet-induced insulin resistance." (PMID 29747466, 2018). "Furthermore, it has been shown that impaired PPARγ action is associated with insulin resistance." (PMID 27023799, 2016). "Although there is evidence that adiponectin can modulate cellular functions in both PPARγ-dependent and -independent fashions, we speculated that PPARγ might be involved in upregulating adiponectin, a molecule that when suppressed is linked to insulin resistance." (PMID 24223187, 2013). "Interestingly, the loss of PPARγ in hematopoietic cells was found to lead to insulin resistance." (PMID 21382489, 2011). "Thus, our findings suggest that rs4607103 near ADAMTS9 may after PPARG Pro12Ala be the second gene locus conferring risk of type 2 diabetes due to insulin resistance." (PMID 19789630, 2009). "However, muscle-specific knockout of PPARγ causedwhole-body insulin resistance." (PMID 17389764, 2007). "Paradoxically, chronic IL-1β exposure leads to sustained NF-κB activation, which subsequently suppresses PPARγ and C/EBPα expression, ultimately inhibiting adipogenesis and inducing insulin resistance." (PMID 41508030, 2026).